TNF (tumor necrosis factor)
Diseases named in the same sentence as TNF in open-access papers (continued):
Sharing a sentence is not in itself a finding about the gene and the disease.
tumor (continued). "Recent studies have emphasized the role of pro-inflammatory cytokines, such as TNF-α and IL-6, in promoting immune system-mediated tumor clearance." (PMID 38252337, 2024). "TNFα and NF-κB also showed a large intra-tumor variability, suggesting the spatial segregation of myeloid cells in the TME." (PMID 39161957, 2024). "The ligands for TNFR1 and Fas (TNF and FasL, respectively) are largely produced by immune cells and are prevalent within the inflammatory tumor milieu." (PMID 39615678, 2024). "The expression levels of TNFα were found to be significantly (p < 0.01) higher in tumor bearing mice compared to tumor-free mice." (PMID 39394174, 2024). "Several reports have suggested that field cancerization is due to chronic and local inflammations, as tumor-secreted inflammatory factors including IL-6, TNF-a and iNOS induced the oncogenic gene expression in the adjacent normal cells 14-16." (PMID 38169511, 2024). "These pathways include releasing perforin, granzyme, interferon‐gamma (IFN‐γ), tumor necrosis factor‐alpha (TNF‐α), and other factors that initiate the tumor cell apoptosis pathway." (PMID 38234174, 2024). "This study found that TNF‐α was responsible for activating GSTO1 expression in macrophage–tumor coculture condition media." (PMID 38750006, 2024). "For instance, TNF-α stimulates tumor progression by activating NF-kB and, thereby, regulating processes, like invasion, migration, cell proliferation, and the inhibitions of apoptosis and tumor angiogenesis." (PMID 38612423, 2024). "IFN-γ is a cellular interferon that can regulate immune function and inhibit tumor cell proliferation, TNF-α is related to inflammatory response and immune response, and IL-6 is the most central inflammatory factor that links inflammation and tumors." (PMID 39508039, 2024). "Preclinical studies have demonstrated that TNF blockade enhances the therapeutic effect of anti-PD-1 treatment, elevating tumor rejection rates from 20% with anti-PD-1 alone to 75% when combined with TNF inhibition." (PMID 39034318, 2024). "This treatment triggered a Th1 cytokine shift characterized by increased IFN-γ and TNF-α levels and decreased IL-4 levels, suggesting a robust anti-tumor response." (PMID 39294673, 2024). "Butyrate and propionate can increase the intratumoral T cells and TNF-α and reduce histone deacetylases (HDACs), increasing chemosensitivity, tumor apoptosis, and cell growth inhibition, migration, and invasion." (PMID 39022585, 2024). "The release of proinflammatory cytokines, such as IL-1, IL-6, IL-8, and TNF-α, by immune, stromal, and tumor cells activates tumor proliferative and pro-survival signaling pathways, such as NF-κB and STAT3." (PMID 38473997, 2024). "It triggered apoptosis and reduced further damage to tumor cells while enhancing the levels of cytokines like TNF-α, IL-2, and immune cells, including macrophages, lymphocytes, and NK cells." (PMID 38794206, 2024). "Another study found that in a mouse model of B16.SIY tumor, B. longum increased production of proinflammatory cytokine tumor necrosis factor alpha (TNFα) and significantly improved tumor control after anti-PD-L1 treatment." (PMID 38361936, 2024). "MACC1, in particular, has been identified as one target initiated through the tumor-promoting effects of two major regulators: the cytokines tumor necrosis factor (TNF)-α and IFN-γ." (PMID 38611008, 2024). "TNF-α can effectively improve inflammatory factors or oxidative stress indicators, promote cardiomyocyte contraction, and decrease tumor activity indicators." (PMID 38711438, 2024). "This study indicates that pDC within the tumor can enhance anti-cancer immune activity, primarily through modulating pro-immune cytokines, reducing Treg cells, and directly curbing tumor growth via TNF- α." (PMID 38638156, 2024). "It involves tumor necrosis factor α (TNFα) signaling in tumor-specific T-cells during the T-cell-mediated immune response to cancer cells." (PMID 38672652, 2024).
tumor (continued). "Considered that TNF-α, which was increased in M1-iBMDM, possesses the effect of promoting tumor cells apoptosis, it is reasonable that iBMDM induced apoptosis of tumor cells through cytotoxic cytokine such as TNF-α." (PMID 38650937, 2024). "Among the Th1 cytokines, tumor necrosis factor (TNF), a critical cytokine that is required for an anti-tumor immune response, was induced at significantly higher levels by toripalimab (1.85-fold) than pembrolizumab (1.42-fold)." (PMID 38400933, 2024). "A notable immediate effect of PDT is the surge in neutrophils, attributed to Tumor necrosis factor α (TNFα) induced by ROS, marking the beginning of the immune system’s assault on the tumor." (PMID 38646546, 2024). "These cells can secrete cytokines, including interferon-γ (IFN-γ) and tumor necrosis factor-α (TNF-α), and can directly eliminate tumor cells through mechanisms like Fas/FasL and antibody-dependent cell-mediated cytotoxicity (ADCC)." (PMID 38576617, 2024). "This process acts as a vicious cycle, in which M2-type TAM cells are stimulated by the tumor itself, releasing factors like TNF and interleukins such as IL-6, IL-1b, and IL-10, which promote tumor proliferation and survival." (PMID 38248305, 2024). "TNF-α mediates the stabilization of PD-L in tumor cells, which prevents PD-L-1 from being ubiquitinated and degraded, necessitating NF-κB p65-induced COP9 signalosome 5 (CSN5)." (PMID 38660299, 2024). "Macrophages are tumor-promoting cells acting by secreting cytokines, such as IL-6, IL-1β, and TNF-α." (PMID 39064019, 2024). "The TNF pathway, crucial for inflammatory responses, was upregulated in interactions among immune cells, reflecting the body's intensified response to the tumor, indicative of efforts to inhibit its growth." (PMID 39468431, 2024). "Research has indicated that tumor cells secrete cytokines, such as granulocyte colony-stimulating factor (G-CSF), interleukin-1β (IL-1β), interleukin-6 (IL-6), and tumor necrosis factor (TNF), which are believed to extend the lifespan of neutrophils." (PMID 39143953, 2024). "The high levels of ROS produced by mitochondrial dysfunction can stimulate tumor cells to release TNF-α, IL-6, and IL-1β, which attract suppressive immune cells and directly damage effector immune cells, reducing their activity." (PMID 39130746, 2024). "Our investigation revealed that that DSTN+CD4T and FLNA+CD4T cells interact with tumor cells through the TNF-TNFRSF1A signaling pair, thereby facilitating tumor migration." (PMID 38292868, 2024). "iCAFs, driven by secreted IL-1 and TNF-α and located more distantly from the tumour, are generally confirmed as tumour-promoting cells through secretion of inflammatory cytokines and growth factors, stimulating proliferation, metastasis, and chemoresistance." (PMID 38920685, 2024). "Smac mimetic, an inhibitor of IAP2 and XIAP, acts through TNF-α secreted by BCG-stimulated neutrophils to promote BCG-induced killing of tumor cells, and the combination of the two drugs effectively promotes the treatment of bladder cancer." (PMID 39253578, 2024). "The IL-12/TNFα combination led to the most pronounced delay in tumor growth, least metastatic lung nodules, and greatest survival." (PMID 38803496, 2024). "The PI3K/Akt signaling pathway also promotes TNF-induced endothelial cell migration and regulates tumor angiogenesis." (PMID 38918540, 2024). "In the early stages of cancer development, TNF-α can stimulate the immune system, attack cancer cells, and lead to apoptosis of tumor cells." (PMID 39246660, 2024). "As an illustration, the cargo of fatty acids carried by tumor EVs and particles (EVPs), specifically palmitic acid, induces the secretion of tumor necrosis factor (TNF) by Kupffer cells." (PMID 38726015, 2024). "When using UALCAN to examine CK expression in HNSCC from the TCGA database, it is evident that IL-1β, IL-10, and TNF are highly expressed in tumor tissues with statistical significance (P < 0.01)." (PMID 38920620, 2024).
tumor (continued). "This tumorigenic effect of TNF-α is based on the generation of ROS and RNS, which cause DNA damage and promote tumor formation." (PMID 38892375, 2024). "Especially, TNFR2 converts the tumor inhibiting ability of TNF-α into a tumor advocating factor, thereby directly promoting the proliferation of some types of cancers such as lung, breast, colon, and skin cancer." (PMID 38592583, 2024). "Activated macrophages can secrete cytokines, such as TNF-α and NO, or act as antigen-presenting cells to facilitate the destruction of tumor cells by activating cytotoxic T cells." (PMID 38335385, 2024). "The involvement of ILC1s and TNFα in tumour development is further demonstrated through the observation that skin precancerous papilloma-associated ILC1 populations have the greatest ratio of TNFα+ cells to IFNγ+ cells, resulting in net pro-tumoural effects." (PMID 38745765, 2024). "Collectively, the CD19 CAR-UiNK cells exhibit a significant enhancement in the secretion of IFN-γ and TNF-α, as well as an increased expression of CD107a upon stimulation by tumor cells." (PMID 39664387, 2024). "Partially exhausted CD8+ T cells have been defined as cells that can produce IFN-γ but lack the ability to produce TNF-α and IL-2, a phenotype consistent with tumor-infiltrating CTLA-4hiPD-1hiCD8+ T cells." (PMID 39273452, 2024). "Th1 cells are known for their role in the production of IFN‐γ, IL‐2 and TNF‐α, among other cytokines, making them the primary Th cell subset involved in the anti‐tumour immune response." (PMID 38898693, 2024). "The groups of CDEVs and CDEVs-PTX showed a rise in the production of GzmB, IFN-γ, and TNF-α, which provides support for the good tumor suppression effect." (PMID 39811730, 2024). "Our research identifies emerging hotspots in mitochondrial-related tumor immunology, focusing on apoptosis activation, cell cycle regulation, and cutting-edge nanotechnologies such as “tumor necrosis factor”." (PMID 39104527, 2024). "By contrast, mast cells inhibit tumor growth releasing cytokines and growth factors, including tumor necrosis factor-alpha (TNF-α), transforming growth factor beta (TGF-β), interferon-alpha (IFN-α), and bioactive monoamines." (PMID 39749033, 2024). "The mechanism of ADCC involves NK cells recognizing B cell IgG-specific tumor cells and inducing target cell death by releasing perforin and granzyme or through the Fas/FasL pathway or TNF-α/TNFR-I pathway." (PMID 38550587, 2024). "The Bi + mAb treatment increased the serum levels of IL-6 as well as TNF-α levels at the tumor site, which mediated inflammation." (PMID 39010088, 2024). "Outnumbering neutrophils, bacteria escape from the necrotic focus into viable tumor cells, multiplying, intensely colonizing the tumor and extending TNF-α synthesis and necrosis." (PMID 38715617, 2024). "The results showed that inhibiting macrophage-derived TNF-α and IL-1β decreased the growth of tumor cells and SPP1-NC also exhibited the secretion of TNF-α and IL-1β." (PMID 39726047, 2024). "The most studied signaling molecules involved in MSC tumor-tropism are tumour necrosis factor-α (TNF-α), interleukin (IL)-6, and stromal cell-derived factor-1 (SDF-1)." (PMID 38169524, 2024). "M1-like macrophages, “fighter” macrophages, in the immune response produce pro-inflammatory cytokines like IL-12 and TNF-α and generate reactive oxygen species (ROS) that attack tumor cells, promoting antitumor immunity and inhibiting tumor growth." (PMID 39200315, 2024). "The use of the CBG+CBD system, especially to treat keratinocytes previously exposed to the UVA, reduced the levels of NFκB subunits and its transcriptional product, the cytokine TNFα, which also plays a key role in skin photoaging." (PMID 38891097, 2024). "TNF-α is known to be an effective tumoricidal cytokine for inducing the apoptotic cell death of tumor cells and inhibiting the tumor growth in a dose-dependent manner." (PMID 38932378, 2024).
tumor (continued). "Our results showed that astragaloside IV-PESV was able to inhibit tumor growth by inhibiting NF-κB, TNF-α and IL-6." (PMID 38622523, 2024). "In cases that are resistant to corticosteroids and disease-modifying anti-rheumatic drugs (DMARDs), anti-tumor necrosis (anti-TNF) biologic agents are usually added." (PMID 38800327, 2024). "For instance, TNF-α induces both apoptotic and necrotic cell death in a variety of cell types, potentially promoting immune-related anti-tumor response." (PMID 39411143, 2024). "M1 are pro-inflammatory macrophages that act as tumor suppressors by releasing large amounts of pro-inflammatory cytokines (e.g., IL-1β, TNF-α, and IFN-β) accompanied by driving the immune response of powerful T cells and cytotoxic cells." (PMID 38553639, 2024). "In patients with NSCLC, TAMs were found to be more oxidative and to promote tumor cell glycolysis by secreting TNF‐α." (PMID 38411356, 2024). "TNF-α plays an important role in all stages of tumor development and is also involved in the functional regulation of the tumor microenvironment and immune resistance." (PMID 39193386, 2024). "When compared to treatment with surgery in rechallenge studies, all mice treated with the IL-12 and TNFα microspheres rejected the tumor, whereas only 20% of mice who had received surgery remained tumor-free." (PMID 38803496, 2024). "The amount of inflammatory cytokine IL-1β, TNF-α, and Il- 18 in tumors leads to severe tumor growth suppression; IL-18 plays an essential role in immunity against pathogens." (PMID 38654309, 2024). "At the same time, we also found the upregulated of TNF-α via NF-κB and inflammatory response pathway in NET positive neutrophils, suggesting the different anti-tumor mechanism caused by NETosis." (PMID 38769374, 2024). "As expected, CD19 CAR-UiNK cells exhibited elevated production of IFN-γ and TNF-α compared to iNK cells when stimulated with Nalm-6 tumor cells." (PMID 39664387, 2024). "Under the influence of IFN‐γ, IL‐6, and so forth, M1 macrophages can inhibit tumor cells by releasing soluble enzymes, TNF and IFN and activating T cell immune responses, showing proinflammatory, antigen presentation and antitumor effects." (PMID 39233637, 2024). "As noted by us and others, it is possible that Irf6 modulates tumor cell sensitivity to death stimuli including TNF in part by participating in or reversing the EMT state." (PMID 38378697, 2024). "TRAIL is released by neutrophils in response to pro‐inflammatory stimuli, such as IL‐8 and TNF‐α,29 and can induce apoptosis in tumour cells and contribute to tumour immunosurveillance." (PMID 38481033, 2024). "A recent single-cell study of MCs across cancers divided tumor MCs into two subtypes: protumorigenic MCs, characterized by a low TNF+/VEGFA+ ratio, and antitumorigenic MCs, characterized by a high TNF+/VEGFA+ ratio." (PMID 39840068, 2024). "On the opposite side, VEGF-A suppresses pro-inflammatory T-cell infiltration into the tumor through inhibition of NF-κB and TNF-α-induced downregulation of CXCL10 and CXCL11." (PMID 38726320, 2024). "TNF-α also induces MMP-9 expression which enhances tumor cells’ ability to migrate and invade other tissues." (PMID 38935134, 2024). "For example, TNF-α can not only activate immune cells, but also promote tumor angiogenesis and immunosuppression in some cases." (PMID 39735340, 2024). "The elevated gene expression in immune cells, notably T cells and B cells, in “Response to tumor cell” and “Positive regulation of tumor necrosis factor production” pathways, indicates a vigorous immune response to cancer cells." (PMID 39468431, 2024). "Polyphenols like curcumin (from turmeric) and quercetin (from fruits and vegetables) reduce the secretion of cytokines driving inflammation, such as TNF-α, IL-6, and IL-1β, related to prolonged inflammation response and tumor progression." (PMID 39683540, 2024).
tumor (continued). "Many studies have focused on the role of cytokines and cytokine receptors as potential targets for tumor intervention, including the inhibition of the tumor-promoting functions of IL-1β, IL-6, and TNF." (PMID 38317842, 2024). "Most notably, among the receptors, the aberrant expression of tumor necrosis factor (TNF) receptor 2 (TNFR2, TNFRSF1B) on the TME cells activates several signaling pathways after the interaction with its ligand, TNF, that support the tumor growth." (PMID 39609700, 2024). "It has been documented that, NK cells and TNF-α are key elements of anti-tumor innate immune response." (PMID 40259956, 2024). "These macrophages release various cytokines and effector molecules such as IL-12, TNF-α, and NO, which suppress tumor cell proliferation, induce apoptosis, and activate other anti-tumor immune cells." (PMID 38894865, 2024). "Cytokines play a crucial role as mediators in the TME, with cytokines involved in adaptive immune responses (e.g., IFNγ, IL-2, IL-12, and TNF) positively impacting anti-tumor immunity." (PMID 38928150, 2024). "We then validated that DRP-104 reduced exhausted T cell populations and improved the functionality of T cells in the tumor microenvironment, as demonstrated by increased IFNγ and TNFα expression." (PMID 38536921, 2024). "On the other hand, the optimal induction of NOS2 and COX2 in murine and human tumor cells requires IFNγ, and its combination with TNF-⍺ and IL-1β was more effective than with LPS." (PMID 38892290, 2024). "At the tumor microenvironment level, treatments with AgNPs-G and doxorubicin significantly increased (p ≤ 0.05) the levels of TNF-α, IFN-γ, and IL-6 compared to the control group." (PMID 39126001, 2024). "CD8+ T cells play a pivotal role in the body’s antitumor processes, releasing perforin to kill tumor cells and secreting cytokines like TNF to regulate the antitumor response, with mitochondria playing a multifunctional role throughout." (PMID 39104527, 2024). "Reactive oxygen species (ROS) produced by myeloid cells stimulate the tumor secretion of TNFα, which, in turn, drives the release of proinflammatory cytokines, creating a vicious loop of tumor-promoting factors." (PMID 38473997, 2024). "The proinflammatory cytokines of IL‐1β, IL‐17, MIF, and TNF‐α were significantly increased in tumor represented complex immunity dysregulation and possible molecular mechanisms due to dysbiosis of the microbiome." (PMID 38041547, 2024). "TNFα seems to be also important for T-cell proliferation, and TNF-α-mediated signaling in T cells were found to be critically required for effective priming, proliferation, and recruitment of tumor-specific T cells." (PMID 39056014, 2024). "Lastly, TNF was found up-regulated (15 MBq/30 MBq) and classified as an apoptosis-related gene, since TNF is involved in both tumor-suppressing and -promoting signaling pathways, depending on its binding to TNFR1 or TNFR2, respectively." (PMID 38826727, 2024). "After 16 days, tumor tissue was processed, and an increase in M1 markers and a decrease in M2 markers, as well as an increment in pro-inflammatory cytokines such as TNF-α and a reduction in immune-suppressing cytokines IL-4, IL-10 and TGF-β, were measured." (PMID 39061247, 2024). "TNF is mainly secreted by macrophages, can induce cell death in certain tumor cell lines, and is mainly involved in the inflammatory response." (PMID 39064924, 2024). "IL-1 and TNF, often elevated in the tumor milieu, play significant roles in inflammatory processes and have been shown to engage specific transcription factors that bind to the BCAR3 promoter region." (PMID 38730626, 2024). "It has been recently shown that MET induced by tumour-derived tumour necrosis factor (TNF)-α promotes anti-carcinogenic activities in neutrophils." (PMID 39421445, 2024).